CX3CL1 (C-X3-C motif chemokine ligand 1)
Description:
Chemokine that acts as a ligand for both CX3CR1 and integrins ITGAV:ITGB3 and ITGA4:ITGB1. The CX3CR1-CX3CL1 signaling exerts distinct functions in different tissue compartments, such as immune response, inflammation, cell adhesion and chemotaxis. Regulates leukocyte adhesion and migration processes at the endothelium. Can activate integrins in both a CX3CR1-dependent and CX3CR1-independent manner. In the presence of CX3CR1, activates integrins by binding to the classical ligand-binding site (site 1) in integrins. In the absence of CX3CR1, binds to a second site (site 2) in integrins which is distinct from site 1 and enhances the binding of other integrin ligands to site 1. [Processed fractalkine]: The soluble form is chemotactic for T-cells and monocytes, but not for neutrophils. [Fractalkine]: The membrane-bound form promotes adhesion of those leukocytes to endothelial cells. (Microbial infection) Mediates the cytoadherence of erythrocytes infected with parasite P.falciparum (strain 3D7) with endothelial cells by interacting with P.falciparum CBP1 and CBP2 expressed at the surface of erythrocytes. The adhesion prevents the elimination of infected erythrocytes by the spleen (Probable).
Synonyms: NTT; SCYD1; NTN; C3Xkine; ABCD-3; CXC3C; CXC3; fractalkine; neurotactin
Tractability: Small molecule: a structure with a bound ligand is known. Antibody: a drug acting on it is in phase 2 or 3 trials; UniProt places it where antibodies can reach, with high confidence; its Gene Ontology location is reachable by antibodies, with high confidence; UniProt predicts a signal peptide or a membrane-spanning region; the Human Protein Atlas places it where antibodies can reach. PROTAC: its protein half-life has been measured.
Target class: Secreted protein
Gene: Protein-coding gene on chromosome 16 (57,372,477 to 57,385,044, forward strand). Ensembl gene ENSG00000006210.
Subcellular location: Cell membrane; Secreted (Processed fractalkine)
Subcellular location (Human Protein Atlas): Plasma membrane; Predicted to be secreted
Pathways (Reactome):
Signal Transduction: Chemokine receptors bind chemokines; G alpha (i) signalling events
Gene Ontology:
Molecular function: chemoattractant activity; chemokine activity; CX3C chemokine receptor binding; CXCR1 chemokine receptor binding; integrin binding; protein binding; CCR chemokine receptor binding; signaling receptor binding
Biological process: cell adhesion; cell chemotaxis; chemokine-mediated signaling pathway; chemotaxis; integrin activation; leukocyte migration involved in inflammatory response; microglial cell proliferation; negative regulation of apoptotic process; negative regulation of apoptotic signaling pathway; negative regulation of cell migration; negative regulation of hippocampal neuron apoptotic process; negative regulation of tumor necrosis factor production; positive chemotaxis; positive regulation of actin filament bundle assembly; positive regulation of calcium-independent cell-cell adhesion; positive regulation of canonical NF-kappaB signal transduction; positive regulation of cell population proliferation; positive regulation of inflammatory response; positive regulation of MAPK cascade; positive regulation of microglial cell migration; positive regulation of phosphatidylinositol 3-kinase/protein kinase B signal transduction; positive regulation of release of sequestered calcium ion into cytosol; regulation of lipopolysaccharide-mediated signaling pathway; antimicrobial humoral immune response mediated by antimicrobial peptide; autocrine signaling; and 31 more
Cellular component: cell surface; extracellular region; membrane; plasma membrane; cell projection; neuronal cell body; perinuclear region of cytoplasm; cell body; neuron projection
Genetic constraint (gnomAD): Loss-of-function variants: 3 observed, 13.44 expected, observed/expected ratio (o/e) 0.22, 90% interval 0.1 to 0.58. The upper end of that interval is the gene's LOEUF score, 0.58, which puts it in group 2 of 6, group 1 being the genes least tolerant of losing a copy. Missense variants: 505 observed, 532.4 expected, observed/expected ratio (o/e) 0.95, 90% interval 0.88 to 1.02. Synonymous variants: 255 observed, 228.92 expected, observed/expected ratio (o/e) 1.11, 90% interval 1 to 1.24.
Homologues: Orthologues: chimpanzee CX3CL1 (98% identical), macaque CX3CL1 (94% identical), rabbit CX3CL1 (69% identical), dog CX3CL1 (67% identical), rat Cx3cl1 (67% identical), mouse Cx3cl1 (65% identical), guinea pig CX3CL1 (63% identical), zebrafish cxcl32b.1 (10% identical). Paralogues in human: CCL21 (11% identical), CCL2 (9% identical), CCL11 (9% identical), CCL7 (9% identical), CCL8 (9% identical), CCL13 (8% identical), CCL24 (8% identical), XCL1 (8% identical), XCL2 (7% identical), CCL25 (7% identical), CCL4 (7% identical), CCL17 (7% identical), and 14 more.
Diseases named in the same sentence as CX3CL1 in open-access papers:
CX3CL1 is named in the same sentence as 396 diseases in open-access papers, as found by Europe PMC text mining. Sharing a sentence is not in itself a finding about the gene and the disease. The quoted sentences say what the papers report.
atherosclerosis (75 papers, 2011 to 2025). A disease characterized by the build-up of fatty material and calcium deposition in the arterial wall resulting in partial or complete occlusion of the arterial lumen. "The CX3CL1/CX3CR1 axis has been implicated in the development of atherosclerosis and cardiovascular disease, but until now, scarce data are available regarding the influence of the CX3CL1/CX3CR1 axis in familial combined hyperlipidaemia (FCH)." (PMID 41153665, 2025). "One of the axes implicated in the development of atherosclerosis and cardiovascular disease is the CX3CL1/CX3CR1 axis." (PMID 41153665, 2025). "Polymorphisms in the Cx3cl1 receptor, Cx3CR1, have been identified as genetic risk factors for atherosclerosis, and the deletion of Cx3cl1, Cx3CR1 and Cxcl1 suppresses atherogenesis." (PMID 38473793, 2024). "Meanwhile, CX3CR1 can bind to fractalkine (FKN; also known as CX3CL1) and modulate the secretion of insulin and atherosclerosis associated with insulin resistance." (PMID 34269146, 2021). "The upregulation of CX3CL1 in HAEC is in agreement with the notion that CX3CL1-mediated attachment and recruitment of leukocytes is operative in vascular inflammation associated with atherosclerosis and arterial injury." (PMID 26710229, 2015). "CX3CL1, which has a major pathogenic role during atherosclerosis, was detected in aneurysmal adventitia where it is produced by vascular endothelial cells such as BECs in response to TNFα." (PMID 24587165, 2014). "In addition, in atherosclerosis, many studies have shown that CX3CL1/CX3CR1 signaling was implicated in angiogenesis during plaque microvessel formation." (PMID 37248293, 2023). "CX3CL1, also known as fractalkine, initiates recruitment of monocytes in the atherosclerotic plaque and has been associated with plaque rupture, unstable angina pectoris and atherosclerosis at all stages." (PMID 31114450, 2019). "Epidemiological human studies revealed that decreased activity of the CX3CL1/CX3CR1 pathway due to genetic factors may be associated with a lower risk of atherosclerosis as well as a decreased incidence in the episodes of plaque destabilization." (PMID 25959742, 2015). "Monocyte recruitment via chemokine receptors has been linked to the development of inflammatory diseases such as atherosclerosis and cancer, and an increased expression of the monocyte/macrophage chemoattractant CX3CL1 has been observed in cardiovascular disease and Alzheimer's disease." (PMID 25105870, 2014). "CX3CL1, also known as fractalkine, is a chemokine with chemotactic activity for monocytes, T cells, and NK cells in the development of numerous inflammatory conditions in obesity-associated chronic complications such as atherosclerosis, insulin resistance and Type 2 diabetes." (PMID 34948325, 2021). "CCL17 has been previously shown to drive atherosclerosis through suppression of regulatory T-cell functions and Cx3cl1 is an established as a pro-atherogenic chemokine." (PMID 40893367, 2025). "Since the CX3CL1/CX3CR1 axis is primarily expressed on endothelial and cardiac cells, it has been implicated in the athogenesis of diseases such as atherosclerosis and heart failure." (PMID 40936920, 2025). "The role of the CX3CL1/CX3CR1 axis in atherosclerosis and cardiovascular disease has been demonstrated in different studies." (PMID 41153665, 2025). "This association seems to be influenced by the presence of IR, which induces a worse metabolic profile, aggravates atherosclerosis, and upregulates the CX3CL1/CX3CR1 axis." (PMID 41153665, 2025). "In line with this, another study revealed that FKN/CX3CL1 was substantially expressed at very early stages of atherosclerosis, which further points to its key role in the initial stages of lesion development, in addition to its relevance in advanced disease." (PMID 38612695, 2024).
atherosclerosis (continued). "In particular, we focus on its role in the processes of inflammation, coronary microvascular dysfunction and atherosclerosis in order to elucidate the influence of FKN/CX3CL1 on vascular endothelial function." (PMID 38612695, 2024). "Our results were verified by qPCR for the selected cytokines involved in immune cell activation and migration (CCL2, CCL3, CCL4, CCL5, CX3CL1), representing potential therapeutic targets in atherosclerosis." (PMID 38256102, 2024). "STAT1 activation in endothelial cells upregulated the expression of inflammatory factor IL-1β and chemokine CX3CL1, triggering atherosclerosis progression." (PMID 38315275, 2024). "These cells are implicated in the acceleration of atherosclerosis, potentially through FKN/CX3CL1 release." (PMID 38612695, 2024). "In CX3CR1‐deficient mice, the CX3CL1/CX3CR1 axis is involved in the progression of atherosclerosis, as CX3CR1 deficiency reduces lesion formation in atherosclerosis." (PMID 37452512, 2023). "For example, atherosclerosis can induce the expression of Vcam-1, Icam-1, Cxcl12, and Cx3cl1 in SMCs, which in turn facilitates binding to monocytes." (PMID 37686377, 2023). "As the only member of the CX3C chemokine receptor subfamily, CX3CR1 binds to its sole endogenous ligand CX3CL1, which shows notable potential as a therapeutic target in atherosclerosis, cancer, and neuropathy." (PMID 35767622, 2022). "This suggests CX3CL1 plays a pivotal role in atherosclerosis both in the early and late stages of the disease." (PMID 33503867, 2021). "CX3CL1, been suggested to be anti-inflammatory and neuroprotective 29, is a potential mediator of both atherosclerosis and metabolic disease." (PMID 33456354, 2021). "Under pathological conditions, the unbalanced regulation of CX3CL1 promotes the inflammatory cascade and promotes the formation of atherosclerosis." (PMID 33456354, 2021). "The primary mode of action of CX3CL1/CX3CR1 in atherosclerosis seems to be recruitment of monocytes and accordingly in this model there was a marked reduction in the macrophage content of the plaques." (PMID 29641559, 2018). "Atherosclerosis is ameliorated in ApoE-/- mice in which the CX3CL1/CX3CR1 pathway has been genetically deleted or pharmacologically blocked." (PMID 29641559, 2018). "CX3CL1 is broadly expressed in brain, it plays a role in a wide range of diseases, including cancer, vasculitis, neuropathies, atherosclerosis, inflammatory diseases, and in human immunodeficiency virus infections." (PMID 30545297, 2018). "Studies disrupting the chemokine pathway CX3CL1 (fractalkine)/ CX3CR1 have shown decreased atherosclerosis in animal models but the techniques used to interrupt the pathway have not been easily translatable into human trials." (PMID 29641559, 2018). "Pharmacological inhibition of the chemokine receptor, CX3CR1 has furthermore been described to inhibit leukocyte recruitment and to reduce atherosclerosis, indicating an important role of CX3CL1 in the pathogenesis of atherosclerosis." (PMID 28234900, 2017). "Inhibition of the CX3CL1/CX3CR1 signaling pathway ameliorated the severity of atherosclerosis in animal models." (PMID 25959742, 2015). "CD40 and CX3CL1 have a well-established role in the pathogenesis of vascular inflammatory disorders such as atherosclerosis and neointima formation after arterial injury." (PMID 26710229, 2015). "Significant changes in the activity of the genes that code for TNF-α and CX3CL1 have been reported at the site of atherosclerosis." (PMID 25959742, 2015). "Our work indicates that CX3CL1 and GM-CSF may represent putative biomarkers of inflammation associated with atherosclerosis, such as C-reactive protein, but are mechanistically tied to atherosclerosis based on the well established findings in animal models of atherosclerosis." (PMID 24995121, 2014).
atherosclerosis (continued). "Evidence from CX3CL1-/-, CX3CR1-/-, and CX3CR1 pharmacologic inhibition studies in mice with a background of hypercholesterolemia mechanistically tied CX3CL1 to atherosclerosis." (PMID 24995121, 2014). "In humans, CX3CR1 polymorphisms in the coding region of the gene are a genetic risk factor for early onset coronary artery disease, strongly supporting a mechanistic role for CX3CL1 in the pathogenesis of atherosclerosis." (PMID 24995121, 2014). "Both CX3CL1 levels, and CD3+CD8+ CX3CR1+ T cell levels increase in patients with chronic coronary artery disease and acute coronary syndromes with plaque rupture, strongly supporting a link between CX3CL1 and atherosclerosis in humans." (PMID 24995121, 2014). "Collectively, the signals that elevate CX3CL1 levels coincide with increased IL-8 and neutrophil levels, which are mechanistically tied to atherosclerosis." (PMID 24995121, 2014). "Fractalkine (CX3CL1) and its receptor, CX3CR1, have also been implicated as modulators of both HIV infection and atherosclerosis, and functional polymorphisms in CXC3R1 (V249I and T280M) are clinically relevant during the course of these conditions." (PMID 23659629, 2013). "Administration of NaHS at either the early or the advanced stage of atherosclerosis suppressed the aortic expression of CX3CL1 and CX3CR1, together with reduced plaque size and IMT thickness in the main branches of the aortic arch." (PMID 22815945, 2012). "To further demonstrate the involvement of H2S in regulating CX3CL1 and CX3CR1 expression during atherosclerosis and to establish its pathophysiological relevance in vivo, we examined the effect of H2S on CX3CL1 and CX3CR1 expression in fat-fed apoE−/− mice." (PMID 22815945, 2012). "Hence, if being considered as biomarker, FKN/CX3CL1, holds a great potential to detect early atherosclerosis." (PMID 38612695, 2024). "In contrast, Cxcl1 and Cx3cl1 have been reported to promote atherosclerosis." (PMID 38473793, 2024). "IL-7Rαlow EM CD8+ T cells also produce much higher levels of IFN-γ and TNF-α and were found to have increased expression of inflammatory chemokine receptors such as CX3CR1 which binds its ligand CX3CL1 (fractalkine), a chemokine involved in inflammatory conditions like atherosclerosis." (PMID 36544153, 2022). "Blocking the CX3CL1/CX3CR1 pathway in in vivo studies ameliorated the severity of atherosclerosis." (PMID 35350534, 2022). "CX3CL1 also promotes excess secretion of cell adhesion molecules and chemokines that promote adhesion to and infiltration of monocytes to the vascular endothelium and accelerate the development of atherosclerosis." (PMID 36310615, 2022). "In addition, the CX3CL1/CX3CR1 axis is a central player in inflammatory disorders such as atherosclerosis development." (PMID 34504250, 2021). "In this report, we define a novel model of CD8 T cell involvement in atherosclerosis whereby CX3CL1 and IL-15 operate in tandem within the vascular endothelium to promote infiltration by activated CX3CR1+ memory CD8 T cells that drive further endothelial activation via TNF." (PMID 32976527, 2020). "To assess the effect of blocking the CX3CL1/CX3CR1 pathway on atherogenesis we developed a DC-targeted DNA vaccination against CX3CR1 that was used in a murine model of atherosclerosis,feeding the mice a normal chow diet to more closely mimic the atherosclerotic lesions found in humans." (PMID 29641559, 2018). "Moreover, knockout or inhibition of CX3CL1 in atherosclerosis-prone mice has demonstrated that the chemokine is critical especially for the recruitment of monocytes at these sites of reduced shear stress." (PMID 28522896, 2017). "Taken together lipid profile, kidney and inflammatory markers CX3CL1 and MPO are associated with rIMT status, which supports our hypothesis that rIMT could serve as a surrogate marker for atherosclerosis." (PMID 28881821, 2017). "Several lines of evidence indicate a role for CX3CL1 in the pathogenesis of atherosclerosis." (PMID 24995121, 2014).